CD4 (CD4 molecule)
Diseases named in the same sentence as CD4 in open-access papers (continued):
Sharing a sentence is not in itself a finding about the gene and the disease.
tumor (continued). "In contrast, tumor growth was significantly inhibited in mice adoptive transferred with Loxoribin-treated DCs, compared with that in mice adoptive transferred with Tregs and CD4+CD8− or CD4−CD8+T cells." (PMID 25593198, 2015). "Meanwhile, part of CD4+T cells has the ability to kill tumor cells directly." (PMID 26161392, 2015). "In addition to the critical role of T helper cells for CD8+ cell priming and expansion, CD4+ cells have also been suggested to be major mediators of immunological tumor cell death." (PMID 25949894, 2015). "Transcriptional analysis confirmed that the CD4+ T cells found in cHL are under the influence of PGE2, and these effects account for at least part of the impaired immune functions associated with the tumor." (PMID 25941795, 2015). "Therefore, heightened IL-6 appeared to act predominantly on tumour-specific CD4+ T cells in aged mice." (PMID 25850032, 2015). "The combination of activation of two co-stimulatory molecules induces a strong effector immune response by primary CD8-positive T cells that is sufficient to attack established tumors, induce CD4-positive T-cell responses, and generate tumor-specific T-cell memory." (PMID 26579494, 2015). "Besides, a rise of CD8+ T and CD4+ T cells in the tumor zone was observed, indicative of tumor-specific acquired immunity." (PMID 26648599, 2015). "Whether this particular population of CD4+ T cells is increasing tumor bone metastases by affecting the OCs or also by inducing an immune suppressive environment needs to be established." (PMID 26000310, 2015). "Furthermore, T cell stimulation through GITR attenuates Treg-mediated suppression or enhances tumor-killing by CD4+ and CD8+ effector T cells." (PMID 26605342, 2015). "Notably, all CD4+ T cell subsets remained at very low proportions in the spleens in both tumor models, although they had varied distribution levels during tumor development." (PMID 25968569, 2015). "As CD4+ T cells could directly recognize MHC class II positive and NY-ESO-1-expressing tumor cells, one would then question the underlying mechanism of how this intracellular antigen is processed to CD4+ T cells." (PMID 26441969, 2015). "It was hypothesized that IL-6 upregulated in aged mice altered the cytokine production by tumour-specific CD4+ T cells to prevent them from attacking the tumours." (PMID 25850032, 2015). "In addition, CD4+ T cells are essential for the priming of tumor-specific CTLs and maintaining anti-tumor responses." (PMID 26556756, 2015). "Thus, our work is unique in showing that human tumor-recognizing CD4+ T cells have an important role in controlling tumor progression." (PMID 26447332, 2015). "This intermediate effect could be explained by the diversity and opposing effects of the CD4+ T cell subsets present in the tumor microenvironment, including anti-tumoral Th1 cells and immunosuppressive T regulatory (Treg) cells." (PMID 26236689, 2015). "However, when immunized in aged IL-6−/− mice, their efficacy was significantly improved, suggesting that increased IL-6 levels in aged hosts dampened the function of tumour-specific CD4+ T cells." (PMID 25850032, 2015). "The PD-1/PD-L1 interaction inhibits T-lymphocyte proliferation, survival and effector functions (cytotoxicity, cytokine release), induces apoptosis of tumor-specific T-cell and promotes differentiation of CD4 T-cells into Tregs and tumor cell resistance to cytotoxic T-lymphocytes (CTL) attack." (PMID 26175923, 2015). "CD4+CD25+Foxp3+ natural regulatory T (Treg) cells might play critical role(s) in the suppression of anti-tumor immune response and thus shed light on tumor progression from benign to malignant." (PMID 26020249, 2015). "Also, 2-DG significantly prevented the tumor induced augmentation of T-regulatory cells (CD4+CD25+) which corresponds to increase in CD8+ (CTLs) cells." (PMID 26135741, 2015). "Another important factor affecting clinical outcomes in NSCLC might be tumor infiltrating CD4+ T cells." (PMID 26604855, 2015).
tumor (continued). "In addition, tumor cells can directly interfere with the immune system by releasing immunosuppressive factors or recruiting immunosuppressive cells, such as CD4+CD25+ Foxp3+ Tregs into the tumor microenvironment." (PMID 26551021, 2015). "In addition, all CD4+ T cell subsets markedly increased in tumor draining lymph nodes at the late stage of 4T1 tumor progression, whereas in E0771-bearing mice, only CD4+IL17+ and CD4+Foxp3+ subsets had significant increases in tumor draining lymph nodes." (PMID 25968569, 2015). "In contrast, rejection is associated with massive infiltration of the tumor bed by leukocytes, predominantly ED1+ microglia/macrophages, CD4+ T helper cells and CD8+ effector cells, and correlates with elevated serum levels of pro-inflammatory cytokines IL-1β, IL-18 and TNF-α." (PMID 26291724, 2015). "However, the discovery of regulatory T cells (Treg) and Th17 cells not only changes the classical Th1/Th2 paradigm of Th cell differentiation, but also markedly alters conventional thinking regarding the role of CD4+ T cells in anti-tumor immunity." (PMID 25968569, 2015). "To further evaluate the tolerability of this combination, we determined whether it also kills normal circulating human lymphocytes, particularly CD4+ T cells, whose preservation can mediate anti-tumor immune responses and improve treatment responses." (PMID 26460954, 2015). "Furthermore, in the E0771 model, the peak of CD4+IFN-γ+ was observed much earlier than that in the 4T1 tumor model with tumor progression, suggesting the dynamic differences of Th1 cells in these two models." (PMID 25968569, 2015). "We next determined whether CD4+ T cell subsets in the other organs could have similar profiles as those in the tumor sites." (PMID 25968569, 2015). "We hypothesize that the oncogene/suppressor role of p42 and p48 EBP1 isoforms, in different cells type, influences the variable MHC II expression by solid tumours, necessary to stimulate a tumor-specific immune-response of CD4+ T cells." (PMID 26081906, 2015). "The CD4-centric nature of our CIRC highlights that CD4+ T cells may be important in CRC anti-tumor immunity." (PMID 25949894, 2015). "Furthermore, more rapidly increased infiltration of CD4+ T cells than that of CD8+ T in the tumor sites was observed with the tumor progression." (PMID 25968569, 2015). "Likewise, depletion of CD8 or CD4 T cells eliminated the ability of anti-OX40 mAbs to induce tumor regression in several tumor models." (PMID 25763356, 2015). "However, the depletion of CD8+ T cells abrogated this antitumour effect, suggesting that therapeutic effect of tumour-specific CD4+ T cells in IL-6-neutralized aged mice was mediated through CD8+ T cells." (PMID 25850032, 2015). "However, when CD4+CD25+Tregs were adoptively transferred into mice, tumor cells again grew progressively and more rapidly than in mice receiving CD4+CD8− or CD4−CD8+T cells alone." (PMID 25593198, 2015). "CD4+ Th1 lymphocytes elicit anti-tumor activity, both directly by killing cancer cells after identification of cancer antigens in the context of MHC class I molecules and by releasing cytolytic molecules, and indirectly by activating cytokine release from macrophages." (PMID 25801067, 2015). "In contrast, there were approximately equal numbers of CD4 T cells in all of the tumor groups." (PMID 25879689, 2015). "The rest of the cells that were not positively stained for either CD4 or CD8 are most likely tumor associated macrophages." (PMID 25460506, 2015). "DC vaccines that activate CD4+ helper T cells simultaneously may be useful to further improve tumour antigen-specific CTL response." (PMID 26471005, 2015). "CD4+CD25+FoxP3+ Tregs are also found in the tumor microenvironment." (PMID 26528477, 2015). "This epitope induced potent cytolytic activity of CD4 T cells against such tumor cells." (PMID 26538233, 2015).
tumor (continued). "Although cytotoxic CD8 T cells have been considered to be the main protagonists in the production of anti-tumor therapeutic effects resulting from vaccines, increasingly, several aspects of CD4 T-cell biology suggest that this T-cell population can effectively be used for cancer immunotherapy." (PMID 26350591, 2015). "This might occur via switching of tumor infiltrating CD4+ T cells to Foxp3+ Tregs by the high TGF-β level present in the immunosuppressive environment of the tumor." (PMID 26109431, 2015). "Treg and Th17 cells are the predominant CD4+ T cells within tumor microenvironments." (PMID 26583116, 2015). "However, comprehensive understanding of the role of CD4+ T cells in anti-tumor immunity is challenging in tumor immunology research and the results have been controversial." (PMID 26587366, 2015). "Indeed, activation of APCs in vivo with an antibody to CD40 has been shown to overcome CD4+ T cell anergy in some tumor models." (PMID 25875653, 2015). "The SUSD4-expressing tumor-infiltrating cells were identified as CD4+ and CD8+ T cells." (PMID 26480818, 2015). "Tumor recognition by HER-3-reactive CD4 T cells is enhanced after the broad inhibition of the HER family, suggesting that such an inhibitor may serve as an immunotherapy adjuvant." (PMID 26538233, 2015). "We found that CD4-depleted mice treated with CRTE6E7L2 DNA vaccine had a significantly greater percentage of E7-specific CD8+ T cells among total CD8+ T cells compared to naïve or untreated tumor-bearing mice." (PMID 24594273, 2014). "In addition, there was a corresponding increase in tumor-infiltrating CD8+ T cell infiltrate while CD4+ T cells and macrophages (defined as CD45+/CD11b+/F4/80hi/Ly6Clow/MHCII+) were unchanged." (PMID 24652403, 2014). "Moreover, the ratio of Th2:Th1 CD4+ T lymphocytes present at the tumor site was negatively correlated with patient survival." (PMID 24672527, 2014). "Other CD4+ T cells may be important for B cell activation and autoantibody production within the tumor microenvironment such as CD4+CXCR5+ Tfh cells." (PMID 24762633, 2014). "Furthermore, the number of E6- and E7-specific CD8+ T cells among splenocytes was significantly greater in CD4-depleted mice treated with CRTE6E7L2 DNA vaccine compared to naïve or untreated tumor-bearing mice." (PMID 24594273, 2014). "Shown to inhibit proliferation of B16 murine melanoma cells in vivo and in vitro, it is thought to have antitumoural effects via anti-angiogenic and pro-apoptotic functions and by enhancing tumour antigen presentation and potentiating CD4+ T cell-mediated tumour cell targeting." (PMID 24969320, 2014). "To investigate whether these numerous CD4+ T-cell specificities are functional redundant or fulfill complementary roles in tumor defense, we assessed their tumor-protective potential in a preclinical PTLD model." (PMID 24853673, 2014). "The first round of treatment may induce tumor cell killing and the release of tumor antigen into the tumor microenvironment as well as the generation of PADRE-specific CD4+ T cells." (PMID 25531529, 2014). "Others have also reported CD4 helper independent CD8+ T-cell anti-tumor activity." (PMID 25119341, 2014). "It is also clear that adoptive cell therapy (ACT) through the use of CD8+ cytotoxic T lymphocyte (CTL) or CD4+ TH cells may both result in durable anti-tumor activity." (PMID 25629004, 2014). "However, immunization of B6 mice with live MCA-205-OVA, MCA-205-E1A-Δp300-OVA and MCA-E1A-OVA tumor cells induced nearly equivalent OVA-specific CD4 T cells and CD8 CTL responses." (PMID 24614600, 2014). "We propose that CD8− restricted and possibly even CD4− T-cell mediated inhibitory signals played only a minor role in our setting and that cell cycle inhibition, preventing expansion of tumor-specific clones and limited IFN-γ production, are likely to constitute an explanation of our observations." (PMID 24757283, 2014).
tumor (continued). "The transformation of CD4+ T cells into Treg cells is an inducer of tolerance to tumor vaccination." (PMID 25310154, 2014). "CD4+ T helper 17 (Th17) cells play dynamic roles in inflammation and tumor immunity." (PMID 24987392, 2014). "Likewise, all tumor growth was abrogated in IT treated CD4+ CTRL and CD4 KO mice whereas most tumors displayed progressive outgrowth in vehicle treated mice." (PMID 25119341, 2014). "Additionally, FLH-treated mice demonstrated increased IFN-γ production and higher numbers of tumor-infiltrating CD4+ lymphocytes." (PMID 24466345, 2014). "Because CD4 T cells can directly kill tumor cells, expanding cells specific for the target tumor antigen may be beneficial." (PMID 24690990, 2014). "Overall, the interference with tumor-induced suppression of CD4+ and CD8+ T cell responses, due to VSSP administration, could be contributing to the antitumor activity of this adjuvant in MCA203 TB mice." (PMID 24829762, 2014). "IL-17 is a CD4 T cell-derived proinflammatory cytokine that may enhance tumor suppression by signaling Th17 cells into the brain tissue." (PMID 24997057, 2014). "TGFβ is reportedly responsible for accumulation of CD4+Foxp3+ regulatory T cells (Tregs) in tumor." (PMID 24416401, 2014). "Preliminary data show a difference in intra-tumoral cytokine profiles in such animals, and a difference in phenotype of cells infiltrating the re-challenged EMT6 tumor in WT mice compared with those infiltrating a primary tumor challenge, with increased CD4+ cells." (PMID 25409195, 2014). "TCR-transgenic models employed in studies of anti-tumor CD4+ T cell responses." (PMID 24782871, 2014). "N1/28z mediated also anti-tumor activity when expressed in CD4+ human primary T-cells." (PMID 25431955, 2014). "Although the SEREX method facilitated the identification of tumor antigens that could be recognized by antibodies and CD4+ T cells, few of their T-cell epitopes have been determined." (PMID 24366042, 2014). "Tumor regression was observed in mice treated with anti-CD4 or rat IgG." (PMID 24642245, 2014). "Indeed, less IFN-γ and/or IL-2-producing CD4+ T cells were detected, and concomitantly, less efficiency against tumor challenge was found when the booster injections were carried out without AS15 (data not shown)." (PMID 24830315, 2014). "Use of TCR-Tg models for studies of anti-tumor CD4+ T cell immune responses." (PMID 24782871, 2014). "The results suggest that the increased population of CD4+Foxp3+LAP+ Tregs in CRC may play an important role in regulating anti-tumor immune response." (PMID 25268580, 2014). "In these studies we proposed that EGFR inhibitors might be effective adjuncts for cancer immunotherapy because these drugs increased MHC-II expression levels on tumor cells, which should enhance CD4+ T cell recognition." (PMID 25240937, 2014). "Since the highly functional TILs resulting from PROSTVAC immunotherapy greatly outnumbered the tumor-associated regulatory CD4 Treg population, PROSTVAC immunotherapy considerably increased the ratios of CD4 and CD8 effector T cells to suppressive Treg cells (Teff : Treg ratio) in the tumors." (PMID 25328681, 2014). "However, significant increases in senescent T-cell populations were induced in preactivated naïve CD4+ T cells in 586mel tumor-bearing mice (over 50%), indicating that human tumor cells can induce naive T-cell senescence in vivo." (PMID 25231413, 2014). "In addition, pretreatment of MCF7 cells with Poly-G3, but not control Poly-T3, significantly reversed the suppressive activity of tumor-induced senescent CD4+ T cells on the responding T-cell proliferation." (PMID 25231413, 2014). "At 21 or 25 days after tumor implantation, splenic Tregs (CD4+CD25+FoxP3+) were analyzed." (PMID 24642245, 2014). "Tumor-antigen signals, together with costimulatory molecules and cytokines, could effectively trigger the activation and functioning of CD4+ and CD8+ T cells." (PMID 24741609, 2014).
tumor (continued). "Anti-tumor immunity consists of antigen-specific CD4+/CD8+ T cell immunity and humoral immunity." (PMID 24568553, 2014). "Furthermore, GAP27, a peptide known to specifically block gap junction formation, dramatically decreased the calcein AM positive T-cell populations in CD4+ T cells co-cultured with calcein AM-labeled tumor cells." (PMID 25231413, 2014). "The results showed that, in contrast to peripheral-derived γδ T cells, tumor-activated γδ T cells induced significantly higher proliferation of CD4+ T cells (n = 3, P < 0.01) and CD8+ T cells (n = 3, P < 0.01) in a number-dependent pattern, as assessed by the reduction in CFSE signals." (PMID 24741609, 2014). "In contrast, secretion of tumor-specific antigen and presentation (perhaps by another type of host APCs) in lymph nodes, may favor induction of potent primary anti-tumor CD4+ T cell responses." (PMID 24782871, 2014). "The depletion of CD4+ T cells also diminished the antitumor effect, indicating an important role of CD4+ helper T cells in tumor protection by 2 mAb treatment considering concomitant removal of expanded Treg by anti-CD4 depleting antibody and the key role of Treg in suppressing antitumor immunity." (PMID 24586709, 2014). "After 20 days, we dissociated skin-draining lymph nodes and re-stimulated lymph node lymphocytes with Her2/neu peptides, mitomycin C-treated BR5FVB1 tumor cells, or BR5FVB1 tumor cell lysate, and performed flow cytometric analysis for the presence of Granzyme B-generating CD4+ and CD8+ T cells." (PMID 24565018, 2014). "Post-therapeutic analysis of tumors excised from mice treated with combination therapy showed decreased numbers of blood microvessels in the tumor microenvironment, lowered numbers of regulatory T lymphocytes, as well as showed higher levels of CD4+ and CD8+ as compared to control mice." (PMID 24220932, 2014). "The numbers of senescent T cells generated from naïve CD4+ T cells dramatically decreased when naïve CD4+ T cells were separated from tumor cells (MCF7, M628 and PC3) in a Transwell system, although the percentages of senescent T cells were still higher than those in the culture medium only group." (PMID 25231413, 2014). "Their accumulation may be due to the proliferation of pre-existing Tregs in the tumor microenvironment, the recruitment of Tregs from periphery, and the de novo conversion of tumor-infiltrating CD4+ lymphocytes into iTreg." (PMID 24938080, 2014). "Furthermore, treatment of tumor cells with Poly-G3, but not LPS or PBS, markedly reversed the suppressive activity of senescent CD4+ T cells induced by tumor cells in 586mel-bearing mice." (PMID 25231413, 2014). "In addition, there is increasing awareness that CD4+ regulatory T cells (Tregs) play an important role in inhibiting anti-tumor immunity." (PMID 25503774, 2014). "This review paper has focused on CD4+ T cell-mediated eradication of tumor cells." (PMID 24782871, 2014). "The role of CD4+ T cells was initially investigated in experiments where tumor-bearing mice were treated by adoptive transfer of T cells obtained from syngeneic mice immunized with irradiated tumor cells, or with living tumor cells followed by surgical resection." (PMID 24782871, 2014). "However, following the administration of a BRAFi in patients with melanoma, tumor biopsies demonstrated a higher infiltration of both CD4+ and CD8+ T lymphocytes within 2 weeks of treatment initiation." (PMID 29250602, 2014). "Thus, adoptive transfer experiments using primed CD4+ T cells generated by immunization with tumor cells conferred protection against a subsequent tumor challenge." (PMID 24782871, 2014). "These CD4+ T-cells would have likely produced Th1 cytokines, like IFNγ and IL-2, stimulating X5563-specific effector T-cell clones already present in the animal allowing for cytotoxic responses to the tumor." (PMID 24949488, 2014).